CD80 (CD80 molecule)
Diseases named in the same sentence as CD80 in open-access papers (continued):
Sharing a sentence is not in itself a finding about the gene and the disease.
pancreatic cancer (18 papers, 2012 to 2024). "A second important phenotype caused by Pik3ca loss or AKT inhibition in pancreatic cancer cells is upregulation of CD80 on the cell surface." (PMID 31112530, 2019). "Data have shown that the CD80 of pancreatic cancer cells is upregulated after treatment with TGF-β, and this is required for migration and invasion of pancreatic tumor cells in vitro." (PMID 39575257, 2024). "Further studies are needed to identify the mechanisms downstream of PIK3CA and AKT that are responsible for downregulating MHC I and CD80 in pancreatic cancer cells." (PMID 31112530, 2019). "However, CD80 expression is higher in pancreatic carcinoma tissues than in normal pancreatic tissues, and CD80 is significantly correlated with the pathological grade and tumor-node-metastasis stage." (PMID 31440272, 2019). "In order to show the regulatory effect of our nanomedicine on macrophage phenotypes, we analyzed the CD80+ (M1-like) and CD206+ (M2-like) populations in the F4/80+ macrophages from the treated pancreatic tumors." (PMID 35177078, 2022). "A large number of CD206 and CD163 positive macrophages, more than CD80 and CD86, were observed in the WT pancreatic tumor and in the corresponding liver metastasis sections, suggesting the relevant presence of M2 macrophages." (PMID 34681678, 2021). "Based on our current understanding, systemic pharmacological inhibition of all PI3K isoforms should enhance the immunogenicity of the pancreatic tumors by upregulating MHC I and CD80, but inhibitory effects on cytotoxic T cells will negate these beneficial changes." (PMID 31112530, 2019). "Furthermore, blockage of CTLA-4/CD80 interaction is sufficient to induce CD4+ T cell infiltration into pancreatic tumours, demonstrating that the CTLA-4/CD80 axis regulates T cell infiltration in pancreatic cancer." (PMID 35892707, 2022). "Specifically, invasive Tregs in pancreatic cancer can bind to CD80/CD86 on the surface of dendritic cells via surface CTLA-4 to inhibit the function of dendritic cells in tissues, which, in turn, affects the function of cytotoxic CD8+ T cells to suppress immune responses in pancreatic cancer." (PMID 30477520, 2018). "Additionally, gemcitabine treatment in pancreas cancer patients showed no significant changes in proportions of T and B-cells including CD86 and CD80 APCs or CD4+, CD25+ T-cells." (PMID 25889536, 2015).
asthma (16 papers, 2011 to 2025). "AYC-EV (8 mg/kg; G4)-treated asthma-induced mice showed a decrease in the number and expression levels of the surface molecules (CD80, MHC-I) of splenic DCs induced by the OVA challenge." (PMID 36139376, 2022). "Eosinophils have been found to accumulate and become activated in airways of asthma patients or murine models during virus-induced exacerbations, manifested by increased expression of CD80, CD86, and MHC II." (PMID 35185908, 2022). "To explore whether CXCL16 knockout alters the expression of costimulatory cell surface molecules in response to Aspergillus-induced asthma, we detected the expression of CD80 and CD86 of the DCs in lung tissue cells for flow cytometry." (PMID 40050290, 2025). "In human asthma, the CD80/CD86-CD28 axis blockade via intravenous infusion CTLA4Ig may be counteracted by an integral immune compensatory mechanism." (PMID 25177863, 2014). "HDM allergens also engage TLR2 in dendritic cells to upregulate c-kit and costimulatory molecules (CD80/CD86), thereby polarizing Th2 responses and exacerbating asthma." (PMID 40529570, 2025). "In asthma, dendritic cells present antigens to CD4 + T cells by expressing MHC class II molecules and rely on co-stimulatory molecules such as CD40, CD80, CD86 to induce T cell activation." (PMID 38664707, 2024). "The results showed that pulmonary DCs from OVA-sensitized and -challenged mice treated with MSCs showed reduced expression of CD40, CD80 and CD86 compared with those in the PBS-treated asthma group." (PMID 25936350, 2015). "A marked downregulation in the expression levels of CD80, CD86 and MHC class II was observed in the lung DCs of the mice in the anti-NGF group when compared with the mice in the asthma and control IgG groups." (PMID 25289030, 2014). "The expression levels of CD80, CD86 and MHC class II on the lung DCs were found to be upregulated in the mice in the asthma and IgG control groups, as compared with the control group." (PMID 25289030, 2014). "The CD80/CD86-CD28 axis is a critical pathway for immuno-corrective therapy, and the cytotoxic T lymphocyte antigen 4 (CTLA4) is a promising immunosuppressor targeting the CD80/CD86-CD28 axis; however, its use for asthma therapy needs further optimization." (PMID 25177863, 2014). "Some C3 proteins are highly associated with asthma, such as: CD80 influences synthesis of IL-4 and IFN in non-specific bronchial asthma, mutations in IL12A influence cockroach allergy among children with asthma, ADA polymorphisms are related to asthma." (PMID 33008305, 2020). "It has also been demonstrated that CD80 and CD86 are critical and potent stimulators of Th2 differentiation in vitro and that these molecules are essential for the generation of Th2 cells during the sensitization phase in a murine model of asthma." (PMID 25973430, 2015). "However, decreased expression levels of CD80, CD86 and MHC class II were observed in the lung DCs of the mice in the anti-NGF group, as compared with those in the asthma and control-IgG groups, despite increased serum levels of IFN-γ." (PMID 25289030, 2014).
glomerular diseases (16 papers, 2013 to 2024). "Various glomerular disease models associated with proteinuria demonstrated that the detection of CD80 with the increase of urinary CD80 was strongly associated closely with frequent-relapse MCD patients." (PMID 33506028, 2021). "Podocytes are able to express CD80, which is a well-known costimulatory marker needed for activation of T cells, and CD80 expression has been associated with certain glomerular diseases." (PMID 33370294, 2020). "Various glomerular disease models associated with proteinuria have reported the detection of CD80." (PMID 33506028, 2021). "Certain glomerulopathies are associated with increased levels of CD80 (B7-1)." (PMID 27733175, 2016). "Urinary CD80/creatinine values were highest in MCD compared to other glomerular diseases and were increased in DN with proteinuria >2 compared to controls." (PMID 36836532, 2023). "CTLA-4, a protein receptor that binds with CD80 and downregulates the response of CD80, has been suggested as a potential treatment for glomerular disease." (PMID 33506028, 2021). "In general, CD80 cannot be expressed on podocytes, but in some glomerulopathies, its expression on the surface of podocyte is increased." (PMID 33194357, 2020). "In certain glomerulopathies, including diabetic nephropathy, CD80 is expressed by podocytes and tubular cells and the renal excretion is increased." (PMID 27733175, 2016). "In addition, abatacept has also been shown to stabilize β1-integrin activation and reduce proteinuria in podocytes of patients with CD80-positive glomerular disease." (PMID 39575257, 2024). "However, a study involving pediatric and adult patients showed that urinary CD80 is elevated in various glomerulopathies that result in a urinary protein-to-creatinine ratio ≥ 3 g/g." (PMID 36673014, 2023). "Since upregulated podocyte CD80 expression has been observed in several glomerulopathies, increased uCD80 levels are not expected to be diagnostic of Fabry nephropathy." (PMID 27733175, 2016). "Due to the correlation of CD80 and CD86 expression in many glomerulopathies, the B7-1(CD80)-CTLA-4 and B7-2(CD86)-CTLA-4 interactions have been proposed as a molecular target in the treatment of these diseases." (PMID 31177287, 2019). "Urinary CD80 values are significantly higher in patients with relapsing MCD when compared with patients with MCD in remission, other glomerular diseases such as focal segmental glomerulosclerosis (FSGS) or membranous nephropathy, and healthy controls." (PMID 23006339, 2013). "In contrast, four baboon Gal KO TKT recipients that did not receive CTLA-4 Ig developed severe proteinuria, modest glomerulopathy, high levels of urinary CD80, and documented CD80 expression on glomerular podocytes." (PMID 38517040, 2024). "Urinary CD80 correlated positively with nephrotic syndrome, regardless of the type of glomerular disease." (PMID 36673014, 2023). "For instance, the suppression of CD80 expression on podocytes could be the therapeutic interest in MCD, FSGS, and glomerular disease." (PMID 33506028, 2021). "In recent years, several research groups have proposed different urinary biomarkers to differentiate between these glomerular diseases, such as CD80 and TGFβ, but there is not enough evidence to use them in clinical practice." (PMID 28158993, 2017). "Urinary CD80 adjusted for urinary creatinine correlated negatively with baseline serum albumin in all patients, regardless of glomerulopathy (r = −0.5, p < 0.0001), whereas it correlated positively, albeit weakly, with baseline proteinuria (r = 0.31, p = 0.006)." (PMID 36673014, 2023).
myeloma (16 papers, 2014 to 2024). "Mouse anti-human CD80 monoclonal antibodies can specifically recognize tumor cells that naturally express human CD80 molecules, such as Burkitt’s lymphoma cells and multiple myeloma cells." (PMID 39575257, 2024). "Activation of CD28 on multiple myeloma (MM) plasma cells, by binding to CD80 and CD86 on dendritic cells, decreases proteasome subunit expression in the tumor cells and thereby helps them evade being killed by CD8+ T cells." (PMID 38654298, 2024). "Up-regulating the expression of costimulatory molecules such as CD40, CD80/86, 4-1BBL, OX40L, CD70 and B7RP on the surface of myeloma cells can increase the susceptibility of myeloma cells to attack by immune effector cells." (PMID 37275861, 2023). "Our laboratory has previously shown that blood dendritic cells from patients with myeloma are numerically normal but functionally defective as they fail to upregulate CD80 (B7-1) expression after huCD40LT stimulation." (PMID 28337449, 2017). "Similarily, the CD28 receptor on multiple myeloma cells promote survival following interaction with its ligand CD80/CD86 on dendritic cells that is related to PI3K activation and Bim downregulation." (PMID 26405162, 2015). "In addition, TGF-β1 and IL-10 secreted by myeloma have a role in inhibiting CD80/CD86 upregulation during DC maturation." (PMID 38464531, 2024). "During this course, microbial Ags to promote the expression of MHC-II, CD40 and CD80 in myeloma cells may be the most critical step to stimulate tumor clonogenicity." (PMID 31870332, 2019). "While some PD-1+CD8+ T cells secreted IFN-γ in response to myeloma antigens, this number was significantly enhanced either by inclusion of anti-PD-L1 blocking antibody during the assay cell co-culture, or by antigen stimulation with 5T33 myeloma modified to express the co-stimulatory molecule CD80." (PMID 28642819, 2017). "Myeloma peripheral blood DCs(PBDCs) mature with reduced expression of leukocyte antigen (HLA-DR), CD40, and CD80 antigens." (PMID 38464531, 2024). "Other B7 co-inhibitory ligands, such as CD86, CD80, and HHLA2, showed high expression levels in myeloma cell lines relative to the other cancer cell lines, implying that these B7 ligands might serve as potential targets for immune checkpoint therapy." (PMID 34504297, 2021). "Prior studies have confirmed that U266 and primary myeloma cells express B cell membrane markers, including high levels of CD86 and CD54 and detectable levels of HLA-DR, CD40 and CD80, which can be upregulated by IFN-γ combined with microbial Ags or by BCGV alone." (PMID 31870332, 2019). "In vitro irradiation with 500 cGy did not change the galectin-9, MHC class II or CD80 expression on 5T33 myeloma cells." (PMID 25614821, 2015). "Both the APC parent (HMy2) and the hybrid cell lines expressed CD80, CD86, and HLA class II, though they were consistently absent in the myeloma cell line U266." (PMID 31428094, 2019). "PD-L1 is highly expressed on 5T33 myeloma cells, but the ligands for TIM-3 (galectin-9), LAG-3 (MHC class II), and CTLA4 (CD80) are not." (PMID 25614821, 2015). "Similarly, the multiple myeloma cell line, RPMI8226 also found to be CTLA4-FasL resistant, expresses only low surface levels of Fas and CD86, with no CD80." (PMID 25227919, 2014). "Importantly for stimulation of T cell responses, levels of expression of MHC class I and class II were significantly higher, and the T cell costimulatory molecules CD80 and CD86, which were not expressed by the myeloma cell line U266, were expressed on the hybrid cell lines." (PMID 31428094, 2019).
Arthritis (15 papers, 2014 to 2025). Inflammation of a joint. "The defective CD80/86 expression in B cells prevents the development of proteoglycan-induced arthritis." (PMID 37256224, 2023). "We were interested in finding evidence of CD80-expressing synovial cells in arthritis models, such as the CIA and D1BC mouse models." (PMID 36180526, 2022). "Consistent with this, B cell expression of the costimulatory ligands CD86 and CD80 has been shown to be essential for autoreactive T cell activation and development of joint pathology in the proteoglycan-induced arthritis model in mice." (PMID 24470500, 2014). "CD80/86-mediated autoreactive T cell activation by B cells plays an important role in the induction of severe arthritis in this model." (PMID 24551182, 2014). "In this study we analysed the peripheral blood components, i.e. CD14+ monocytes, CD4+, CD8+ and CD56+T lymphocytes (CD3+), CD80+, C-X-C chemokine receptor 3 (CXCR3)+, CD27+ B lymphocytes (CD19+) and CD16+CD56+CD3− NK cells, for their association with arthritis development." (PMID 27629388, 2016). "Costimulatory interactions of CD80 and CD86 to T cells are required for the activation of autoreactive T cells and induction of arthritis." (PMID 31582900, 2019). "GTS-21 treatment ameliorated clinical arthritis in a mouse model of CIA in vivo, decreasing the secretion of pro-inflammatory cytokines in the serum and downregulating CD80 and MHC II expression on DCs in the spleen of CIA mice." (PMID 30486874, 2018). "CD80/CD163 or CD80/CD206 positive cell ratios have been used to immunohistochemically assess macrophage polarization in various conditions such as colorectal cancer, arthritis, aging, lung injury and peri-implantitis." (PMID 36286036, 2022). "Notably, the expression of costimulatory factors (CD80 and CD86) and the MHC-II molecule was significantly increased on B cells from the spleen and lymph nodes in mice with established arthritis on the 35th day after immunization." (PMID 29370826, 2018).
B cell lymphomas (15 papers, 2013 to 2024). "Humans are also known to express soluble CD80 and soluble PD-L1, and high plasma levels of PD-L1 are associated with poor prognosis in B cell lymphomas." (PMID 28515726, 2017). "DLBCL (DLBCL-NOS [not otherwise specified] and TCHRBCL [T cell/histiocyte-rich B cell lymphoma]) and FL samples showed an even higher expression of CD80 and CD86, respectively." (PMID 38340727, 2024). "In summary, these data suggest an increased expression of CD80/CD86 in aggressive B cell lymphomas beyond its physiological upregulation during the germinal center reaction." (PMID 38340727, 2024). "Some researchers have found that the IL-4/anti-CD40 stromal cell culture system can induce high expression of CD80 in low-grade B-cell lymphoma under in vitro culture conditions, indicating that it is a potential immunotherapeutic target." (PMID 39575257, 2024). "Like many B-cell lymphomas, Raji cells express a wide assortment of T-cell costimulatory molecules such as CD80 and CD86." (PMID 37087494, 2023). "Murine A20 B-cell lymphoma cells expressing CD40L have been shown to upregulate CD80, CD86, ICAM-1, Fas and MHC molecules." (PMID 33666760, 2021). "To further assess the anti-tumor efficacy of CTLA4-T cells against primary tumors, we developed B cell lymphoma PDX mouse models by using primary tumor tissues with high CD80 and CD86 expression." (PMID 33868277, 2021). "Contrary to CD86 that stimulates the proliferation of B cells and the production of IgG by B cells in B cell lymphoma, CD80 downregulates the B cell response and secretion of IgG in B cell lymphoma." (PMID 30999581, 2019). "Galiximab is a primatized mAb that is directed against CD80, an antigen that is expressed on the surface of many B cell lymphomas." (PMID 23764770, 2013). "CD80 is transiently expressed on antigen-presenting cells, T cells and activated B cells, but is constitutively expressed on the surface of many B-cell lymphomas." (PMID 23764770, 2013). "We first investigated whether CAR T cell therapy based on 2nd Gen CARs specific for CD19 (Tisagenleceucel, Novartis), CD20 (Miltenyi), and bispecific for CD20 and CD19 (Miltenyi) has an impact on CD80/86 expression on B cell lymphoma tissue." (PMID 38340727, 2024). "Likewise, CD40L gene transfer in B-cell lymphoma cells from patients resulted in enhanced expression of CD80 and CD86 and generation of tumor-specific T-cell response in vitro." (PMID 33666760, 2021). "This is the first report of the evaluation of CD80 expression in canine B cell lymphomas." (PMID 30040869, 2018). "LOAd703 could infect and replicate in B-cell lymphoma cell lines (BC-3, Karpas422, Daudi, DG-75, U-698) and induced an overall enhanced immunogenic profile with upregulation of co-stimulatory molecules CD80, CD86, CD70, MHC molecules, death receptor Fas and adhesion molecule ICAM-1." (PMID 33666760, 2021). "In contrast, the JY and Raji B cell lymphoma cell lines, shown to be highly sensitive to CTLA4-FasL, express high levels of CD80, CD86 and CD95." (PMID 25227919, 2014). "CD80 is expressed on various B-cell lymphomas, including follicular, diffuse, small noncleaved, mantle cell, small lymphocytic, and other subtypes." (PMID 39575257, 2024). "Therefore, we detected the surface expression levels of CD80 and CD86 in Pre-B acute lymphoblastic leukemia (ALL) (NALM6) and B cell lymphoma (Raji and RL) cell lines." (PMID 33868277, 2021). "Anti-CD80 clinical trials have demonstrated clinical benefit with no severe adverse effects in both psoriasis and CD80+ B cell lymphoma, providing proof of concept for in vivo targeting of CD80 in human disorders." (PMID 24472094, 2014).